FASN (fatty acid synthase)
Diseases named in the same sentence as FASN in open-access papers (continued):
Sharing a sentence is not in itself a finding about the gene and the disease.
tumor (continued). "SREBP is a transcription factor that promotes DNL by upregulating key enzymes such as ACLY, FASN, and SCD, which are closely linked to tumor proliferation, apoptosis, and invasion." (PMID 37700339, 2023). "FASN was visually increased in the Cr(VI)-tumor lung tissue as compared to the adjacent normal lung tissue." (PMID 38069382, 2023). "Elevated FASN expression in ovarian cancer cells results in the accumulation of lipids and subsequent inhibition of tumor-infiltrating dendritic cells, which are required to sustain the capacity of anti-tumor T cells." (PMID 38060103, 2023). "At the microscopic level of molecular interactions, JorA combines with two important tumor-promoting molecules, FASN and TOP1, and inhibits tumor progression." (PMID 37587470, 2023). "Fatty acid synthase (FASN) acts as the central member in fatty acid synthesis and metabolism processes, which regulate oncogenic signals and tumor immunogenicity." (PMID 36428733, 2022). "It has been reported that the FA de novo synthesis pathway is generally up-regulated in tumor cells, and FASN overexpression has been an independent prognostic marker for the aggressive clinical course of tumor cells." (PMID 36106108, 2022). "We further confirmed this correlation by analyzing FASN and CS protein levels in matched normal colon and tumor tissues." (PMID 35742953, 2022). "Liu and colleagues found that fatty acid synthase (FASN) can activate lipid metabolism in tumor cells to produce excess amounts of palmitic acid, thereby inhibiting the apoptosis of tumor cells and promoting multidrug resistance." (PMID 35154461, 2022). "Targeting FASN enhances the body’s anti-tumor function through immune-regulation-dependent pathways." (PMID 36555243, 2022). "Our findings further demonstrated a strong correlation between FASN expression and MHCs, 60 immune checkpoint genes, chemokines, and chemokine receptors, suggesting a strong connection between FASN levels and tumor immune regulation." (PMID 36555243, 2022). "Tumour cells accumulate TGs due to upregulated FASN and enhanced lipogenesis, and LD-resident TGs can be used for bioenergetic β-oxidation." (PMID 35954376, 2022). "Orlistat is also a potent FASN inhibitor, and results from a subcutaneous tumor model showed that orlistat treatment inhibited metastatic ability." (PMID 35625633, 2022). "In HER2-positive tumors, HER2 upregulation produces a fatty acid synthase (FASN) activation subtype, which provides sustained FA synthesis and facilitates a tumor proliferative rate." (PMID 36428733, 2022). "Cells with membranes densely composed of phospholipids and saturated fatty acids secondary to fatty acid synthase’s increased activity give tumor cells increased resistance to chemotherapeutic agents." (PMID 35456969, 2022). "The results showed that the growth rate of subcutaneous xenograft tumor cells with PROCR overexpression was suppressed when FASN or PTGS1/2 were inhibited." (PMID 35169126, 2022). "To identify the influence of lipid metabolism on tumor initiating potential in vivo, we administered FASN or PTGS1/2 inhibitors to mice and evaluated xenograft tumor growth regularly." (PMID 35169126, 2022). "TNBC tumor cells overexpress fatty acid synthase (FASN), and the combination of FASN inhibitors and anti-EGFR signaling agents has significant antitumor effects in preclinical models of TNBC tumors." (PMID 36059650, 2022). "FASN expression correlates with OC tumor clinical staging and histological malignancy, and patients showing increased FASN expression have a worse survival rate and platinum resistance." (PMID 35269636, 2022).
tumor (continued). "Clinically, glucocorticoids such as prednisone and dexamethasone can inhibit the expression of FASN and thereby inhibit the proliferation and growth of tumor cells." (PMID 36106108, 2022). "The function of fatty acid synthase (FASN) is crucial in growth and survival of tumours with lipogenic phenotypes." (PMID 36010906, 2022). "By virtue of the distinct lipid metabolism in tumour cells, inhibitors targeting FASN and SREBP have shown great anti-cancer effects in various malignancies." (PMID 36139650, 2022). "And another selective FASN inhibitor, Fasnall, also reduces tumor volumes and extends survival when combined with carboplatin in the MMTV-Neu model of HER2+ breast cancer." (PMID 36172157, 2022). "Complex recent study showed that inhibition of FA biosynthesis with FASN inhibitor orlistat also resulted in higher T effector and reduced Treg tumor infiltration, increased DC maturation and slowed down tumor growth." (PMID 36582801, 2022). "Enhanced histone acetylation levels at the promoter regions of FASN have been reported to promote FASN expression and increase de novo lipid synthesis to promote tumor cell survival, thus supporting its role in EBV‐miR‐BART18‐3p‐dependent CRC progression." (PMID 36307872, 2022). "Studies have shown that FASN inhibition both limits tumor-cell migration and invasiveness, and increases tumor sensitivity to drug therapy." (PMID 36387147, 2022). "IHC staining of the 10 paired tissue samples confirmed that FASN expression was higher in tumor tissues." (PMID 35392075, 2022). "In spite of the emerging importance of FASN as a marker of tumor aggressiveness, a possible pharmacological target, and a prognostic indicator, there are no probes for direct in vivo PET imaging of FASN expression." (PMID 35268652, 2022). "We found that USP22 depletion in HT29 and RKO E6 cells attenuated tumor formation, and reconstituted expression of FASN rescued the inhibitory effect of USP22 depletion on colorectal tumorigenesis." (PMID 36333288, 2022). "LYVE-1 staining showed less lymphatic vascular structure in the tumor site in the sh-FASN group, providing evidence that FASN contributes to LNM in CC." (PMID 35597782, 2022). "Lipid synthesis dependent on FASN has been demonstrated to play a key role in metabolic adaptation to VEGF therapy in different tumor types." (PMID 36551752, 2022). "A study reported that FASN-mediated FA synthesis promotes functional maturation of T regulatory cells, and thus induces immune response suppression and accelerated tumor proliferation." (PMID 36428733, 2022). "Consistent with other literature, the expression of FASN was higher in tumor tissues than in normal tissues." (PMID 36397145, 2022). "Using the CPTAC proteome database, we also examined the differences in FASN protein expression between various tumor tissues and comparable normal control tissues." (PMID 36555243, 2022). "The relationships between FASN expression and tumor stromal, immune, and ESTIMATE scores were examined using ESTIMATE." (PMID 36555243, 2022). "NFKB1, NFKBIA, TNFRSF1A, and FASN were found to be related to DNA repair, which affects tumor sensitivity to DNA-damaging agents." (PMID 35899106, 2022). "Most tumours present high levels of fatty acid synthase (FAS), and higher FAS expression has been correlated with more advanced choroid and optic nerve invasion, high mitotic index, and less differentiated histology." (PMID 35620002, 2022). "To gain insight into the regulatory network of FASN in tumor progression, we analyzed the protein interaction of FASN using the GeneMANIA database." (PMID 36555243, 2022). "Based on RNA-seq data, FASN expression appeared to be lower in normal tissues than basal and tumor tissues." (PMID 35392075, 2022).
tumor (continued). "As a comprehensive understanding of the functions of FASN, it has been discovered that FASN participates in the regulation of the tumor microenvironment as a metabolic regulator, which in turn affects immune cell infiltration or treatment sensitivity." (PMID 36555243, 2022). "Its product is the only human protein to catalyze de novo synthesized long-chain fatty acids, implying FASN plays a crucial role in lipid metabolism in tumor microenvironment." (PMID 35127296, 2022). "Paired-sample analysis revealed higher FASN expression in tumor than normal tissues, in all 10 patients." (PMID 35392075, 2022). "FASN is abnormally expressed in lots of tumors and is highly related to tumor migration and invasion." (PMID 36246597, 2022). "The next-generation FASN inhibitors present limited systemic toxicity in a preclinical study, higher anti-tumor potential and higher specificity for FASN." (PMID 35433453, 2022). "We selected two enzymes of fatty acid metabolism for further investigation, namely, ACSS2 and FASN, which are emerging markers of tumour metabolism." (PMID 36010906, 2022). "In this case, a variety of tumours overexpress FASN, including liver, pancreas, gastric, colorectal, ovarian, breast, and prostate cancer, which is often associated with poor prognosis." (PMID 36139650, 2022). "A recent study of CRC tissues showed that FASN was upregulated in tumours compared to normal mucosa." (PMID 35954376, 2022). "Tumor cells depend on the action of fatty acid synthase (FAS) for de novo fatty acid synthesis for cell membrane genesis." (PMID 35456969, 2022). "In the current study, we demonstrated that an EBV‐encoded miRNA, EBV‐miR‐BART18‐3p, significantly promotes tumor growth and facilitates de novo lipogenesis in CRC by regulating the SIRT1/HIF1α/LDHA/FASN axis." (PMID 36307872, 2022). "Even in the low-expressed LUAD in the TCGA database, the illustrated data show that inhibiting FASN enhances the sensitivity of tumor cells to irradiation, further confirming the oncogenic role of FASN in various tumors." (PMID 36555243, 2022). "FASN is a crucial enzyme for the de novo synthesis of fatty acids, which plays an essential role in lipid metabolism and is correlated with tumor-related signaling pathways." (PMID 36106333, 2022). "Collectively, these findings suggest that FASN is likely a reliable tumor prognostic and immunotherapy marker." (PMID 36555243, 2022). "However, the prognosis of FASN expression in anti-PD-1 immunotherapy and anti-PD-L1 treatment methods is diametrically opposite, which may be due to the different functions of FASN in tumor cells and tumor-associated T cells." (PMID 36555243, 2022). "Fatty acid synthase (FASN), a key enzyme for fatty acid synthesis, is highly expressed in tumor tissues of CRC patients, so it is considered a promising target for CRC treatment." (PMID 35637953, 2022). "It was one of the first natural FASN inhibitory compounds which showed anti-tumor activity in in vitro studies of breast cancer and ovarian cancer xenograft models." (PMID 35628385, 2022). "miR-195 has been demonstrated to play a tumor suppressive role in the occurrence and progression of malignant meningioma by targeting FASN." (PMID 36452489, 2022). "IHC staining revealed that FASN expression was higher in tumor tissues than in normal tissues, and was mainly located in the cytoplasm." (PMID 35392075, 2022). "Clinicopathology grouping analysis, using the GSE3167, GSE40355, GSE32548, and GSE32894 datasets, indicated that FASN was highly expressed in patients with high tumor grades." (PMID 35392075, 2022). "FASN contributes to the maturation of Treg cells and is required for Treg cell-mediated tumor growth, though its role in Treg cell-mediated immune homeostasis is dispensable." (PMID 39872079, 2022). "In bladder cancer, PKM2 interacts with SREBP-1c through the regulation of the Akt/mTOR signaling pathway, which in turn activates FASN transcription for tumor growth." (PMID 35912181, 2022).
tumor (continued). "FASN expression is mostly correlated with tumour characteristics and clinical prognosis of gynaecological cancer patients." (PMID 35448537, 2022). "The combination of bezafibrate and medroxyprogesterone acetate, orlistat, N-phenylmaleimide and methyl jasmonate can all regulate the expression of FASN to inhibit the growth of tumor cells." (PMID 36106108, 2022). "The IHC results were obtained and the results of FASN gene expression in tumor tissues were compared with those in normal tissues." (PMID 34879004, 2021). "For the metabolic alterations, PGM1 expression downregulation suppressed lactate production and facilitated FASN activity in tumor tissues." (PMID 34507580, 2021). "FASN is an attractive therapeutic target, since it is overexpressed in tumor cells compared with normal cells." (PMID 33759347, 2021). "Of note, FASN inhibition has been reported to be selective for tumor cells that rely on the lipids synthesized by FASN for survival, with minimal adverse effects on normal cells." (PMID 34068792, 2021). "As shown by qRT-PCR result, FASN was markedly up-regulated versus that in adjacent non-tumor tissues (P <0.05)." (PMID 35070947, 2021). "The increased abundance of FASN potentially confers tumour cells an advantage in survival and growth." (PMID 33626208, 2021). "Recently, preclinical evaluation showed that FASN is overexpressed in TNBC tumor samples and contributes to doxorubicin and docetaxel resistance." (PMID 34462429, 2021). "fasnall, an anti-tumor agent (fatty acid synthase inhibitor), can stimulate the production of aberrant SGs with high internal mobility and fast turnover.Some anti-tumor drugs increase cell viability by increasing the production of SGs." (PMID 35004322, 2021). "FASN inhibitors, such as cerulenin and orlistat, induce apoptosis and delay tumor growth, and an analogous effect can be obtained from natural sources, such as green tea and soybeans." (PMID 33922558, 2021). "The fatty acid synthase (FASN) is overexpressed in many tumor entities because of tumor cells’ dependency on the “de novo” synthesis of fatty acids compared to normal healthy tissues." (PMID 34885085, 2021). "Interest in FASN-driven lipid signaling as a target for therapeutic intervention stemmed from findings more than a decade ago that tumor cells show reduced growth and viability upon targeted FASN suppression." (PMID 34675185, 2021). "Through human fatty acid metabolism PCR array analysis of xenograft tumor tissue, this study identified several genes involved in phospholipid metabolism, such as FASN, the main target of PCa cell metabolism." (PMID 34977875, 2021). "Another metabolic regulator, FASN promotes proliferation, migration and survival of HLECs and is a key mediator of tumor lymphangiogenesis." (PMID 34831316, 2021). "DCs isolated from OC ascites are characterised by high FASN expression which correlates with defective antigen presenting abilities, resulting in inactivation of anti-tumour T-cells." (PMID 34944851, 2021). "Meanwhile, down-regulation of HIF-1α/fatty acid synthase co-axis was shown to combat tumor growth in mammary gland carcinoma by activating PHD-2." (PMID 35280255, 2021). "The combination of CYH33 with the FA synthase (FASN) inhibitor C75 synergistically inhibited tumor growth with enhanced host immunity." (PMID 34373258, 2021). "Specifically, it has been found that de novo fatty-acid synthesis mediated by FASN determines Treg maturation and if FASN is deleted from Tregs, tumor growth is inhibited." (PMID 34526996, 2021). "Tamoxifen-stimulated growth of MCF-7/Her2-18 tumors was strikingly suppressed in mice treated with the FASN inhibitor C75, which closely phenocopied the tumor growth inhibitory effects of estrogen deprivation." (PMID 33800852, 2021). "High FASN expression correlated with lymph node metastasis, tumor stage status (TNM) and worse prognosis of CRC patients." (PMID 34200820, 2021).
tumor (continued). "Macrophage colony-stimulating factor derived from Lewis lung carcinoma induced FASN expression in TAMs, stimulating tumor growth and angiogenesis in ARG1- and IL-10-dependent manner." (PMID 34742349, 2021). "The tumor cells imported fatty acids from the circulation and reducing fat in the diet synergized with FASN deletion and delayed tumor growth." (PMID 33540663, 2021). "Data from OC murine models indicate that FASN inhibitors can restore sensitivity to cisplatin and tumour proliferation." (PMID 34944851, 2021). "Several next-generation compounds targeting FASN have been developed with less severe side effects and effective anti-tumor effects in preclinical studies." (PMID 34742349, 2021). "FASN is a key regulatory molecule in lipid metabolism and plays an important role in the growth and survival of tumor cells with lipogenic phenotypes." (PMID 34564955, 2021). "In vivo treatment with a FASN inhibitor completely prevented the agonistic tumor-promoting activity of tamoxifen and fully restored its estrogen antagonist properties against ER/HER2-positive xenograft tumors in mice." (PMID 33800852, 2021). "Previous studies in OC also have demonstrated the up-regulation of FASN and its involvement in tumor growth and metastasis." (PMID 33414447, 2021). "FASN-related altered lipid metabolism has long been recognized to occur in tumor cell lines with acquired resistance to chemotherapeutics (e.g., doxorubicin, etoposide, cisplatin and paclitaxel) and HER2-targeted therapies (e.g., trastuzumab and lapatinib)." (PMID 33800852, 2021). "The anticancer activity of cerulenin-mediated FASN inhibition has been extensively investigated using multiple in vivo and in vitro tumor models." (PMID 34765544, 2021). "More impressively, FASN inhibition enhances the sensitiveness of tumor cells to chemotherapy and radiotherapy." (PMID 35070947, 2021). "Then, we further analyzed the correlations between clinicopathological features and ACC1, ACLY and FASN mRNA levels in surgical PTC tumor tissues." (PMID 34158007, 2021). "FASN is a key enzyme involved in the synthesis of FA essential for the de novo synthesis of FA in tumor cells." (PMID 34620841, 2021). "Just recently, CRC tumor tissue has been found to contain highly upregulated FASN, which is supported by our findings both in whole tumors and purified primary tumor cells (this study;)." (PMID 34206240, 2021). "Higher expression of fatty acid synthase (FASN) in cisplatin-resistant tumor cells signals the downstream molecule TGFβ1, resulting in elevated PD-L1 expression that suppresses NK cell functions." (PMID 33262947, 2020). "We specifically selected FASN for our analysis both because of its well-established tumor supporting role in liver carcinogenesis and the fact that FASN is dispensable in the adult liver and, thus, can be suppressed without significantly harming normal cells." (PMID 33187130, 2020). "This extends beyond the increased expression of fatty acid synthase to meet increased energy demands and the need for lipid bilayers, to an ever-increasing understanding of the role of glycerophospholipids in tumour viability, proliferation and metastasis." (PMID 31617102, 2020). "FASN is an essential molecule in the lipid metabolic pathway and is capable of rewiring tumor cells for greater energy flexibility to attain their high energy requirements." (PMID 32872164, 2020). "Increased FASN expression plays a fundamental role in maintaining the stemness, invasiveness and tumor-forming abilities of Glioma CSCs." (PMID 32670883, 2020). "Although the activity of the PI3K/AKT and SREBP1c signaling cascade that regulates FASN expression is similar between normal and tumor cells, tumor FASN expression is found to be insensitive to nutrient levels as opposed to that in normal cells." (PMID 32872164, 2020).